CFTR (CF transmembrane conductance regulator)
Diseases named in the same sentence as CFTR in open-access papers (continued):
Sharing a sentence is not in itself a finding about the gene and the disease.
lung disease (continued). "The CFTR modulators IVA, LUM/IVA, TEZ/IVA, and ELX/TEZ/IVA have been shown to be effective not just in people with mild to severe CF, but even in people with advanced pulmonary disease, such as lung transplant applicants." (PMID 34268058, 2021). "By contrast, in CF humans and CF pigs, ATP12A leads to unchecked acidification of the ASL, which is not neutralized by CFTR-mediated bicarbonate transport in the case of CF, leading to prominent lung disease." (PMID 33986686, 2021). "It is known that the pulmonary disease phenotypes do not correlate well with CFTR genotypes, and that other genetic (e.g., modifier genes) and environment factors (e.g., socioeconomic status) affect the disease severity." (PMID 33567498, 2021). "New-born CFTR-KO pigs and ferrets do not have severe lung disease; however, within weeks or months after birth, they spontaneously acquire bacterial infections in the lung." (PMID 33291484, 2020). "Unfortunately, the currently available CFTR mutant CF mice models do not recapitulate CF lung disease." (PMID 31708925, 2019). "This diminished CFTR activity appears to have minimal negative effects in the rice rat airway, as they show no overt signs of lung disease, even as carriers of hantavirus." (PMID 31491720, 2019). "We do not know the specific mechanism(s) of how the three lung diseases enable miRNAs to destabilize CFTR mRNA." (PMID 31590401, 2019). "Moreover, the size of the airways and the presence of a non-CFTR calcium-activated Cl- channel (CACC) in parallel with CFTR and other dissimilarities in lung disease between humans and mice models can account for differences in resistance to bacteria." (PMID 30662403, 2018). "Although many CF mouse models have been developed, the CFTR Null mouse does not exhibit lung disease, and the β-ENaC mouse is not suitable for gene-addition therapy development because its lungs contain functional CFTR." (PMID 30538635, 2018). "Mutations of CFTR gene have been found in many patients with bronchiectasis and MAC lung disease; although these patients have not a diagnosis of CF, it seems that they have some defects in bronchial mucosal ion and in water transport." (PMID 26106603, 2015). "Proposed mechanisms for the lack of profound lung disease in CF mouse models include alternative chloride channels present in the mouse airway that compensate for CFTR absence and differences in bacterial airway colonization." (PMID 24236172, 2013). "CFTR knockout mice do not develop significant lung disease or a secondary increase in circulating inflammatory cytokines common in CF patients." (PMID 24236172, 2013). "In summary, our studies demonstrate that low levels or absence of CFTR-mediated Cl− secretion aggravate early airway mucus obstruction and pulmonary mortality associated with COPD-like lung disease in βENaC-Tg mice." (PMID 22937152, 2012). "The lack of CFTR activity brings a dysregulated exchange of ions and water through the airway epithelium, one of the main aspects of CF lung disease pathophysiology." (PMID 21994643, 2010). "No lung disease was reported from loss of function of CLC-2, so presumably CLC-2 is not critical for the function of mature respiratory epithelium when CFTR is present." (PMID 15507145, 2004). "While the “culprit” event may be heterogeneous among the various aetiologies of NCFBE and is uncertain in many people (“idiopathic”), CF lung disease originates from dysfunctional or absent CFTR protein at the airway epithelium." (PMID 39293854, 2024). "As treatment was associated with improvements in both bronchiectasis and non-bronchiectatic lung abnormalities, this suggests that CFTR modulators may benefit patients with a range of lung disease severity." (PMID 37113757, 2023). "Thus, gene therapy for CF lung disease remains an attractive approach for treating all the population with CF, not only for other currently lacked of the option of CFTR modulator therapy." (PMID 36304167, 2022).
lung disease (continued). "Thus, the airway inflammatory milieu from late- and early-stage CF lung disease improves the efficacy of CFTR modulators, regardless of the combination therapy used." (PMID 33859562, 2021). "Second, injury to lung epithelia and immune cells in regions with structural lung disease could restrict the beneficial effects of CFTR-targeting therapies to lung regions without such damage." (PMID 34903059, 2021). "The processes leading to mucus dehydration in non-CF lung diseases are incompletely described, but recent evidence suggests that prolonged cigarette smoke exposure reduces CFTR expression, induces CFTR internalization, and disrupts CFTR channel function, leading to ASL dehydration." (PMID 34064654, 2021). "Given the versatility of VX-770 in treating multiple CFTR class defects as well as non-CF lung diseases resulting from acquired CFTR dysfunction, we expect that the additional classification of VX-445 as a CFTR potentiator will have broad impact in the treatment of CF and non-CF lung disease." (PMID 34615919, 2021). "It is noteworthy that there is evidence from animal models that impaired mucociliary clearance due to CFTR dysfunction may lead to lung disease and inflammation even in the absence of infection." (PMID 33816324, 2021). "Thus, multiple processes, in which SFPQ plays a central role, are operating in concert to regulate CF lung diseases, characterized by inflammation, fibrotic factor as well as lack of functional CFTR." (PMID 34404863, 2021). "Although not modulating the functioning of CFTR channels, the Scnn1b-Tg+ mouse model effectively demonstrates how a single ion-channel defect results in an imbalance in ion transport, which ultimately leads to ASL dehydration and associated lung disease." (PMID 31396541, 2019). "In this model, CFTR expression and function are not altered, but nevertheless β-ENaC mice exhibit hallmarks of CF lung disease including mucus hypersecretion, mucus obstruction in the conducting airways, mucociliary clearance impairment, goblet cell metaplasia, and neutrophilic airway inflammation." (PMID 30581723, 2018). "Our findings suggest that the lack of CFTR in AM alone triggers the hyperinflammatory response and the activation of NF-κB in AM and emphasize the potential significance of this cell type in CF lung disease." (PMID 20543983, 2010). "Dysfunction of CFTR in CF airway epithelium perturbs the normal regulation of ion transport, leading to a reduced volume of airway surface liquid (ASL), mucus dehydration, decreased mucus transport (MCT), and mucus plugging of the airways, which are hallmarks of early CF lung disease." (PMID 19621064, 2009). "Taken together, our results show that CFTR-F508del ferrets displayed components of both obstructive (reduced IC and FEV) and restrictive (reduced quasi-static compliance and increased FEV0.4/FVC) lung disease, which may also reflect air trapping and increased residual volume." (PMID 38646935, 2024). "Although HEMT has and will continue to improve outcomes substantially for individuals with CF, many with advanced lung disease could benefit from LTx, and respondents in our study valued feeling informed and prepared for LTx decision-making regardless of lung function or CFTR modulator status." (PMID 39026320, 2024). "Hence, the correction of CFTR-mediated absorption in ionocytes may be not necessary to cure CF lung disease." (PMID 37843282, 2023). "CFTR protein in human airways is predominately expressed in the ciliated epithelium and the submucosal glands, therefore histological disparities between murine and human airways may explain the absence of lung disease in CF mice." (PMID 29609604, 2018). "In the context of CF lung disease, we explored the possibility that CF neutrophils might fail to produce effective NETs, prompted by observations that a number of neutrophil responses are abnormal in the setting of non-functional CFTR." (PMID 21909403, 2011).
lung disease (continued). "Rare non-p.Phe508del CFTR genotypes assessed for ELX/TEZ/IVA - mediated CFTR modulation by sweat test, spirometry and body weight in pwCF with advanced lung disease." (PMID 37025483, 2023).
pancreatic insufficiency (125 papers, 2004 to 2026). "Selective impairment of CFTR-dependent bicarbonate transport, even in the presence of residual chloride conductance, is strongly associated with exocrine pancreatic insufficiency, recurrent pancreatitis and cystic-fibrosis-related diabetes." (PMID 41683706, 2026). "CFRD is particularly common in individuals with severe CFTR (CF transmembrane conductance regulator) variants—especially p.Phe508del homozygosity—which are strongly associated with pancreatic insufficiency." (PMID 41552835, 2026). "Key risk factors include pancreatic insufficiency, female sex, severe CFTR genotypes (such as p.F508del homozygosity), CF‐related liver disease, and family history of type 2 diabetes." (PMID 41552835, 2026). "OW/obese patients (mean age 11.3 years, 61.7% male) included 20 patients (42.5%) with two severe CF-related mutations, 21 (44%) with pancreatic insufficiency, and 40 (85.1%) receiving CFTR modulator treatment." (PMID 41829925, 2026). "Pancreatic insufficiency, a direct consequence of CFTR deficiency, is present in at least 70% of pwCF resulting in fat and liposoluble vitamin malabsorption, abdominal symptoms, weight loss, requiring pancreatic enzyme replacement therapy." (PMID 41134303, 2026). "SPINK1-related SIIEPI also warrants comparison with other genetic forms of early-onset exocrine pancreatic insufficiency, particularly those caused by pathogenic or predisposing variants in CFTR and CEL." (PMID 41009946, 2025). "CF patients carrying CFTR gene mutations often experience pancreatic exocrine insufficiency and impaired fatty acid absorption, leading to abnormally high levels of fatty acids in the intestine." (PMID 41244782, 2025). "Data from a cross-sectional analysis of patients with CF revealed that 25% of those with severe CFTR genotypes (typically associated with pancreatic insufficiency) had a BMI ≥ 25 kg/m2 between 2015 and 2017." (PMID 40981163, 2025). "In 1950, the first instances of pancreatic insufficiency in patients with residual CFTR function due to mutations were documented." (PMID 38611676, 2024). "The nine included PwCF for the functional assays were selected as presenting with severe CF based on their high sweat chloride levels (> 60 mmol/L), exocrine pancreas insufficiency and both CFTR variants belonging to mutation classes I or II." (PMID 39732786, 2024). "Briefly, sex ratio was close to 1/1 and patients were mostly characterized by at least one ΔF508 CFTR mutation, pancreatic insufficiency, chronic MSSA colonisation and altered lung function without significant differences between groups." (PMID 36911035, 2023). "Patients with F508del-CFTR mutations have decreased quantity and function of the CFTR protein leading to severe disease manifestations, e.g., inborn exocrine pancreatic insufficiency, growth impairment, and progressive lung disease." (PMID 37229253, 2023). "Patients with 2 severe CFTR variants tend to have an earlier onset of pancreatic insufficiency and a more severe course." (PMID 37711888, 2023). "Adjusted associations were evaluated using multivariate Cox models adjusting for sex, age of entry into CFFPR, CFTR variant severity, pancreatic insufficiency, CF-related diabetes, maternal education, insurance status." (PMID 37460380, 2023). "It is known that the CFTR mutation causes pancreatic exocrine insufficiency, resulting in the reduced absorption of fat-soluble vitamins, especially K and D, which are essential for bone mineral health." (PMID 35887806, 2022). "Adult patients in this study appeared to be phenotypically somewhat different from the children, with a lower proportion with ‘classical’ CFTR mutations and pancreatic insufficiency." (PMID 34301741, 2022). "The present study found an association between CFTR gene mutations and pancreatic insufficiency, in addition to an association of disease severity with colonization by Staphylococcus aureus and P. aeruginosa and underweight." (PMID 36102402, 2022).
pancreatic insufficiency (continued). "Scientific evidence has shown that CFTR gene mutations are associated with pancreatic insufficiency but have a poor association with respiratory symptomatology." (PMID 36102402, 2022). "Nevertheless, our patient with this CFTR variant combination displayed a classic CF phenotype with pancreatic insufficiency." (PMID 36428953, 2022). "Higher concentrations of total BAs were significantly associated with both CFTR genotype severity and pancreatic insufficiency." (PMID 36293293, 2022). "This surrogate measure classifies the severity of specific CFTR mutations, associating higher scores with pancreatic insufficiency (PI) and, conversely, lower scores to increased risks for pancreatitis." (PMID 36293293, 2022). "The relationship between the severity of the mutations and pancreatic damage has been previously reported by grouping the mutations into classes, associating a higher risk of pancreatic insufficiency in those with variants that cause greater CFTR dysfunction." (PMID 35698092, 2022). "Whereas patients with CF usually develop complete exocrine pancreatic insufficiency, pancreatitis patients with CFTR mutations have mostly preserved exocrine pancreatic function." (PMID 33682322, 2021). "Dysfunctional CFTR contributes to increased energy expenditure, exocrine pancreatic insufficiency causing impaired dietary macronutrient digestion and absorption, intestinal dysbiosis, and impaired bile acid homeostasis." (PMID 34578785, 2021). "The association between low sterols and severe CFTR is in agreement with the very high grade of pancreatic insufficiency in CF patients with the F508del homozygous genotype." (PMID 33669566, 2021). "Mutations in CFTR cause impaired chloride ion transport in the epithelial tissues of patients leading to cardiopulmonary decline and pancreatic insufficiency in the most severely affected patients." (PMID 31978131, 2020). "Because CFTR is abundantly expressed in the exocrine pancreatic and biliary secretory system, mutations in CFTR can result in mucus obstruction in these organs and consequent exocrine pancreatic insufficiency." (PMID 31780953, 2019). "Pathological concentrations of PIVKA-II occurred more frequently in patients with pancreatic insufficiency and those who have two severe mutations in both alleles of the CFTR gene." (PMID 26160248, 2015). "Pathological concentrations of PIVKA-II are found more frequently in patients with pancreatic insufficiency and those who have two severe mutations in both alleles of the CFTR gene." (PMID 26160248, 2015). "Specifically, patients who carry class I-III mutations on both alleles are associated with pancreatic exocrine insufficiency, whereas those carrying at least one class IV-VI CFTR mutation are pancreatic sufficient." (PMID 24225052, 2013). "Specifically, patients who carry class I-III mutations on both alleles are associated with pancreatic exocrine insufficiency (PI), whereas those carrying at least one class IV-VI CFTR mutation are associated with pancreatic sufficiency (PS)." (PMID 24225052, 2013). "CFTR also contributes to risk as MI almost exclusively manifests in CF subjects with exocrine pancreatic insufficiency (PI), which is highly correlated with CFTR genotype." (PMID 22438829, 2012). "Loss of CFTR function results in destruction of the exocrine tissue and eventual pancreatic insufficiency." (PMID 15921521, 2005). "With the exception of pancreatic insufficiency resulting in impaired digestion, other aspects of CF are less readily related to loss of CFTR function." (PMID 15921521, 2005). "It is conceivable that early use of ETI in subjects homozygous for the Phe508del CFTR, who are at high risk of severe manifestations, could prevent the onset of pancreatic insufficiency and potentially bronchiectasis, diabetes and other complications." (PMID 41039909, 2025).